ICAM1 (intercellular adhesion molecule 1)
Diseases named in the same sentence as ICAM1 in open-access papers (continued):
Sharing a sentence is not in itself a finding about the gene and the disease.
melanoma (continued). "Alternatively, ICAM1 overexpression could influence various immune cell subsets, enhance their binding to the luminal surface of the sinusoids, and thus indirectly mediate melanoma cell retention and adhesion." (PMID 39875968, 2025). "Interestingly, a study conducted by Slattery and colleagues revealed the necessity of a functional ICAM-1/Mac-1 adhesion axis accompanied by a cocktail of cytokines responsible for the migration of melanoma cells and favoring the aggregation of melanoma cells to neutrophils under flow conditions." (PMID 38730718, 2024). "Our single-cell RNA-seq data showed that zebularine treatment of melanoma cells significantly upregulated a panel of MHC-AgPPM genes, innate immune-associated genes (IFN-stimulated genes, chemokines, etc.), and genes involved in lymphocyte adhesion (such as Vcam1, Icam1, Icam2, and Sele)." (PMID 38755254, 2024). "Hence, there may be complex consequences of decreasing the expression of ICAM-1 in melanoma, and future studies are needed to clarify this issue." (PMID 34068618, 2021). "We speculate that the differentiation status of wildtype NRAS/BRAF melanomas impacts on the prognostic utility of ICAM-1, as more than three quarters of the wildtype NRAS/BRAF tumors had high PMEL levels and thus were derived from well differentiated melanocytes." (PMID 30116025, 2018). "This could probably further enhance ICAM1 and facilitate the inflammatory environment; b) primary lower miR-222 levels lead to better recognition of melanoma cells by infiltrating lymphocytes due to higher ICAM1 expression, leading to secondary enhanced inflammatory signature." (PMID 26338962, 2015). "Furthermore, melanoma cells produced and secreted high levels of IL8, which attracts neutrophils and increases β-2 integrin expression on their surface, which then interacts with intercellular adhesion molecule-1 on melanoma cells to promote anchoring to the vascular endothelium." (PMID 22719918, 2012). "Hence we noticed that melanoma cells, mainly the A375 and 1205LU cell lines, which have the higher capacities of transmigration, secrete pro-inflammatory cytokines, namely GM-CSF and IL-6, which have been described to up-regulate the expression of ICAM-1." (PMID 23039186, 2012). "Similarly melanoma-conditioned medium activates ICAM-1 expression in endothelial cells." (PMID 23039186, 2012). "In combination with bevacizumab, anti-CTLA-4 enhanced tumor infiltration by promoting E-Selectin, ICAM-1 and VCAM-1 at the surface of melanoma cells." (PMID 40071851, 2025). "CAVATAK, derived from coxsackievirus A21, targets tumor cells with high expression of intercellular adhesion molecule-1 (ICAM-1), commonly found on melanoma cells." (PMID 40352942, 2025). "Two important cell surface molecules, ICAM-1 and DAF, are commonly overexpressed in a variety of cancers, such as glioblastoma, colorectal cancer, triple-negative breast cancer, and melanoma." (PMID 41313526, 2025). "Adhesion of ICAM1 and VCAM1 to melanoma cell integrins creates anchor points, and most intracranial melanomas use vascular co-optation rather than induce angiogenesis." (PMID 41463339, 2025). "As a methodology, SFD is able to reveal well-known proteins in melanoma exosomes that are immune-related and are also surface-expressed proteins, such as CD26 (DPP4), CD44, CALR, B7-H3 (CD276), CSF1, ICAM1, L1CAM, MICB, APOH, TIMP1, and CD39." (PMID 40805206, 2025). "Five hub genes including CXCL11, ICAM1, LEF1, MITF, and STAT1 were identified, SUZ12, SOX2, TCF3, NANOG, and SMAD4 were determined as the most significant TFs in metastatic-melanoma." (PMID 39820173, 2025). "Using the UALCAN tool, we examined the association between hub gene expression and overall survival in melanoma and detected a substantial correlation among high levels of CXCL11, ICAM1 and STAT1 expression and poor prognosis." (PMID 39820173, 2025).
melanoma (continued). "Survival analysis also disclosed that the differential expression of CXCL11, ICAM1, and STAT1 was accompanying through poor prognosis in progressive melanoma." (PMID 39820173, 2025). "Based on the ameliorated TME remodeling and increasing tumoral exposure of ICAM1 antibodies, the impact of DAC on tumor penetration of I1‐DXd was further evaluated in the PDX model of melanoma." (PMID 38874532, 2024). "Upregulations of Cxcl9, Cxcl10, Cxcl11, Ccl5, Tap1, CD74, Irf1, Icam1, CD40, Fas and PD-L1 were detected after Mi-2β silencing and the anti-PD-1 treatment in BRafV600E/Ptennull melanomas." (PMID 38461299, 2024). "A primary example is LFA-1 and ICAM-1, which directly enables the infiltration of CD8+ T cells to CT26 colon cancer and B16 melanoma following increases in local IL-6 and soluble IL-6R." (PMID 38786066, 2024). "In agreement, others report that A375-MA2 melanoma cells form micro-clusters with neutrophils inside blood vessels in MAC-1 and ICAM-1-dependent manners." (PMID 38786066, 2024). "CVA21 exploits the presence of intercellular adhesion molecule-1 (ICAM-1) to bind and infect the host cell, and melanoma has been identified as a cancer type with high ICAM-1 levels relative to normal cells." (PMID 36651961, 2023). "The upregulation of LFA-1 and ICAM-1 promoted the interaction between T cells and exosomes, whereas the inhibition of ICAM-1 on melanoma-derived exosomes reduced this interaction and diminished PD-L1-mediated suppression of T cells." (PMID 36674479, 2023). "In the present study we apply, for the first time, the CCL21+ICAM1 based SIN technology, on human TIL, derived from melanoma patients." (PMID 36937426, 2023). "CVA21 is an enterovirus that preferentially infects melanoma cells since it binds to receptors that are overexpressed on melanoma cells, decay-accelerating factor (DAF) and intracellular adhesion molecule-1 (ICAM-1)." (PMID 36900196, 2023). "Treatment with rm-IL-17A led to increased mRNA expression of key T cell chemokines such as CXCL9–CXCL11, adhesion molecules ICAM1 and VCAM1 and IL-17-dependent cytokines in melanoma cells." (PMID 37525015, 2023). "Once secreted by melanoma cells, HMGB1 binds to RAGE, activating the endothelial cells with consequent increased expression of the adhesion molecules VCAM-1, ICAM-1, and E-selectin." (PMID 36012593, 2022). "CD44/E-selectin-binding signaling upregulates intercellular adhesion molecule 1 (ICAM-1) expression on the cell surface via the PKCα/p38/Sp1 pathway, thereby promoting melanoma cell metastasis." (PMID 35936713, 2022). "ICAM-1, a cell surface glycoprotein and adhesion receptor, was shown to be expressed together with LFA-1 under melanoma-endothelial cell co-culture conditions to facilitate melanoma metastasis in vitro." (PMID 36338621, 2022). "The Yale University Mouse Melanoma 2.1 cell line was transduced with a lentivirus containing human ICAM-1 and isogenic clones were selected and tested for ICAM-1 expression by immunoblotting." (PMID 34503272, 2021). "Activation of melanoma cells by HFD includes induction of the NF-κB pathway, increased expression of adhesion molecules such as ICAM1 and chemokine synthesis, such as CXCL-1, -2 and -5." (PMID 27049717, 2016). "Both ICAM-1 and LFA-1 have been shown to be involved in transendothelial tumour growth in melanoma in vitro models." (PMID 27447568, 2016). "Experimental data so far has suggested that the interactions between ICAM-1 and LFA-1 are primarily responsible for the initial tethering of a melanoma cell to a PMN." (PMID 26366568, 2015). "The results of our study show that melanoma cells display a unique composition of cell surface antigens, including ErbB3, IGF-1-R, CD44 and ICAM-1." (PMID 24489649, 2014). "With blocking antibodies against these integrins and ICAM-1, we showed that LFA-1 promotes melanoma cells transmigration in vitro." (PMID 23039186, 2012).
melanoma (continued). "We provide evidence that melanoma supernatants induce ICAM-1 expression on HUVEC cells, and that LFA-1 can be detected on melanoma cell lines when using HUVEC-conditioned medium." (PMID 23039186, 2012). "Having shown that melanoma cells can induce ICAM-1 expression on HUVEC cells, it was necessary to provide evidence of ICAM-1 implication in the transmigration." (PMID 23039186, 2012). "Melanoma-endothelial cell co-culture induces LFA-1 and ICAM-1 expression, thereby favoring in vitro melanoma trans-migration." (PMID 23039186, 2012). "Further confirmation was obtained through the use of either ICAM-1 or LFA-1 blocking antibodies introduced during the co-culture and show that they strongly impair melanoma transmigration." (PMID 23039186, 2012). "C32 melanoma cells mainly express the CD36 receptor on their surface, and in lesser amounts the receptors ICAM-1 and CSA." (PMID 22205992, 2011). "Flow cytometric analysis confirmed the presence of surface ICAM-1 expression on the four melanoma cell lines SK-Mel-28, SK-Mel-RM, ME4405 and MV3; and also on the ICAM-1 transfected RD cells." (PMID 21241513, 2011). "Melanoma cell adhesion molecule/CD146, Platelet Endothelial Cell Adhesion Molecule-1/CD31, ICAM-1, and ICAM-2 are adhesion proteins participating in the recruitment of leukocytes to sites of tissue injury and inflammation." (PMID 21245959, 2011). "The murine B16 melanoma cell line was confirmed to lack ICAM-1 expression and did not express human B7H3." (PMID 41280875, 2025). "Interestingly, IFN-γ can also upregulate intercellular adhesion molecule-1 (ICAM-1) and PD-L1 on melanoma-derived exosomes, which contributes to the suppression of the T-cell response." (PMID 40108693, 2025). "At the BBB, melanoma cells are able to convert hemodynamic signals into chemotactic responses and are arrested at sites of discontinuity in the tight junctions of the endothelial cells, where VCAM1, ICAM1, and E-selectin are expressed." (PMID 41463339, 2025). "Coxsackievirus A21 (CVA21) is a naturally occurring oncolytic enterovirus that selectively targets and lyses melanoma cells due to its affinity for intercellular adhesion molecule-1 (ICAM-1) and decay-accelerating factor (DAF), which are normally overexpressed on melanoma cells." (PMID 39857682, 2025). "Given decitabine (DAC), a clinically approved DNMT inhibitor, has shown promising efficacy and clinical safety in phase I clinical trials for melanoma, DAC was selected to combine with ICAM1‐ADCs to explore the potential synergistic antitumor efficacy in vitro and in vivo." (PMID 38874532, 2024). "In particular, as compared to B16F1 melanoma, AT-3 tumors were enriched in mediators of leukocyte infiltration, including chemokines like RANTES, MCP-1 and − 5, fractalkine, CXCL9, 10 and 16, as well as endothelial adhesion molecules like ICAM-1 and VCAM-1." (PMID 38493157, 2024). "In the study reported here, we have tested the effect of the CCL21+ICAM1 SIN, on the expansion and cytotoxic phenotype of Tumor Infiltrating Lymphocytes (TIL) from melanoma patients, following activation with immobilized anti-CD3/CD28 stimulation, or commercial activation beads." (PMID 36937426, 2023). "Intercellular adhesion molecule 1 (ICAM-1), for example, promotes the aggregation and retention of T cells in the tumor niche by binding to the β2-integrin LFA-1 in the melanoma xenograft model, which leads to improved immune control and potentially limits tumor development." (PMID 37509684, 2023). "In the context of picornaviruses, a single subcutaneous injection of CVA21 particles expressing the intercellular adhesion molecule-1 (ICAM-1) and the decay-accelerating factor (DAF) resulted in tumor regression and reduced tumor burden in a mouse melanoma model." (PMID 36992407, 2023).
melanoma (continued). "As observed in the melanoma, PDPN+PDGFRα+ CAFs were reorganized but still present in similar numbers in tumors lacking ADAM12+ MSCs, and the vasculature displayed increased pericyte coverage and ICAM1 expression." (PMID 37798557, 2023). "We assessed ICAM-1 (CD54) and VCAM-1 (CD106) expression on melanoma cells by flow cytometry because they may influence responsiveness to 7HP349 therapy." (PMID 35552271, 2022). "Secretion of GM-CSF, DPPIV, ICAM1 and PIGF by melanoma-associated fibroblasts was not reported before." (PMID 35538545, 2022). "A previous study showed that adenosine deaminase acting on RNA 1 (ADAR1) was decreased in melanoma cells and that downregulation of ADAR1 supported melanoma cells to avoid tumor infiltrating lymphocyte-mediated killing by regulating intercellular adhesion molecule 1 (ICAM1)." (PMID 34827646, 2021). "Statistical analysis performed on data obtained from all investigated 14 melanoma and 10 hematological cancer cells showed significant (p < 0.05) differences in MFI of HLA class I and ICAM-1 expression detected after treatment with guadecitabine and DAC, but not with AZA, vs. untreated cells." (PMID 30581389, 2018). "Nonetheless, univariate analysis clearly illustrated the prognostic value of ICAM-1 for MSS in NRAS/BRAF melanoma, where reduced expression is associated with worst survival, a finding that has not been widely reported in melanoma." (PMID 30116025, 2018). "Further investigation indicated that sulphated SIP decreased melanoma cell B16F10 pulmonary metastasis in mice models, and down-regulated expression of the intercellular adhesion molecule 1 (ICAM-1) and basic fibroblast growth factor (bFGF) in lung metastasis nodules." (PMID 29597272, 2018). "Kluger and colleagues proposed a multiplex, plasma-based protein biomarker panel that included CEACAM, ICAM-1 (intercellular adhesion molecule 1), osteopontin, MIA (melanoma inhibitory activity), GDF-15 (growth differentiation factor 15), TIMP-1 (tissue inhibitor of metalloproteinase 1), and S100B." (PMID 27642217, 2016). "Some reports indicate that ICAM-1 and TNF-αare related to melanoma." (PMID 24516588, 2014). "Accordingly blocking antibodies of ICAM-1, CD11a or CD18 strongly decrease melanoma transmigration." (PMID 23039186, 2012). "Our group has showed that α-MSH can inhibit tumour necrosis factor-α (TNF-α)-induced upregulation of intercellular adhesion molecule-1 (ICAM-1) in human melanocytes and melanoma cells and reduce interactions between cytokine-stimulated melanoma cells and T lymphocytes." (PMID 14612916, 2003). "Because our results showed that ICAM-1 upregulation may be predictive not only of a proinflammatory melanoma secretome but also of an immunogenic TME, we then investigated whether ICAM-1high levels correlated with improved prognosis of patients with melanoma." (PMID 39867570, 2025). "Nevertheless, to our knowledge, it has not yet been investigated how modulation of melanoma ICAM-1 expression may affect the TME." (PMID 39867570, 2025). "A study quantified levels of MIA in serum using ELISA in comparison to S100 and soluble intercellular adhesion molecule 1 (ICAM-1) and suggested that MIA was the more sensitive biomarker and found that enhanced MIA serum levels where present in 100% of patients with stage III or IV melanoma." (PMID 39156972, 2024). "Given the results presented here, we propose that the CCL21+ICAM1 synthetic niche, which proved to enhance expansion in the murine OVA systems, and elevate the cytotoxic capacity of murine CD8 cells, is capable to reinforce human TIL, derived from melanoma patients." (PMID 36937426, 2023). "Notably, the presence of a distal primary E0771 tumor but not of an irrelevant distal tumor (e.g., B16 melanoma) totally eliminated the growth of the second primary E0771 tumor but did so irrespectively of ICAM-1 expression by the second primary tumor." (PMID 35911772, 2022).
melanoma (continued). "B16F10 melanoma cells do not express ICAM-1, implying that they cannot engage LFA-1 across the IS." (PMID 35680882, 2022). "Notably, variance in levels of ICAM-1 expression did not determine the infectability of our panel of melanoma cells as confirmed by RT-PCR." (PMID 34503272, 2021). "Moreover, when we analyzed the adhesion of T cells to monolayers of B16-VEGFC melanoma cells, we observed very weak adhesion that did not change regardless of the assays being done in the presence of anti-ICAM-1 antibodies." (PMID 30258446, 2018). "In the B16.F10 melanoma model, endothelial expression of ICAM-1 and VCAM-1 was not changed after treatment with agonistic CD40-antibody or sunitinib alone, but combining these treatments led to a synergistic increase in ICAM-1 (p=0.043) and VCAM-1 (p=0.017) surface expression." (PMID 27385210, 2016). "With enhanced local expression of VCAM-1 and ICAM-1 around B16F1 cell arrest sites in the liver, LPS significantly increased the retention of melanoma cells in the liver, especially in the terminal portal venule regions between 8 and 24 h after intramesenteric injection of melanoma cells." (PMID 16336680, 2005). "Indeed, metastatic derivatives of melanoma cells are negative for ICAM-1." (PMID 39335111, 2024). "Furthermore, fibroblasts activated by melanoma cells showed upregulation of the MMPs’ expression mediators’ levels (pERK, p-p38, CD44, RUNX), enhanced secretion of lactate, several cytokines (IL8, IL6, CXCL1, CCL2, ICAM1), and proteins related to angiogenesis (GM-CSF, DPPIV, VEGFA, PIGF)." (PMID 35538545, 2022). "However, other reports challenged these observations, indicating that PTX might actually enhance NK cell-mediated elimination of tumor cells by increasing NK cell cytotoxicity, by inducing the expression of ICAM-1 and MIC-B and/or by sensitizing melanoma cells to killing." (PMID 34712615, 2021). "The VLA-4 positive and LFA-1 negative integrin profile of melanoma cells differs from CD4+ effector T cells, which do express LFA-1 and use the ICAM-1/LFA-1 axis for crawling on the BBB apical face prior to diapedesis." (PMID 37894438, 2023). "As melanoma cells do not express B2-integrins (LFA-1 or Mac-1) on their surface, these cells can bind to the B2-integrins of neutrophils by their intercellular adhesion molecule-1 (ICAM1), and then move into the vessels." (PMID 34207884, 2021). "Nevertheless, it is evident in melanoma and other cell lines we have tested that CVA21 infection is not detected when ICAM-1 is absent." (PMID 34503272, 2021). "In the area of cancer therapy, Coxsackievirus A21 (CAV21) expressing the intercellular adhesion molecule-1 (ICAM-1) and decay accelerating factor (DAF) decreased tumor burden in non-obese SCID mice bearing melanoma xenografts." (PMID 30832256, 2019). "Related to cancer, Coxsackievirus A21 (CAV21) expressing intercellular adhesion molecule-1 (ICAM-1) and decay-accelerating factor (DAF) reduced tumor burden in nonobese SCID mice implanted with melanoma xenografts." (PMID 29883422, 2018). "In most patients, melanoma cells exhibited ErbB3/Her3, CD44/Pgp-1, ICAM-1/CD54 and IGF-1-R/CD221, but did not express CD20, ErbB2/Her2, KIT/CD117, AC133/CD133 or MDR-1/CD243." (PMID 24489649, 2014). "The expression of ICAM-1, VCAM-1, E-selectin and αv integrin was all induced to different degrees by the growth of melanoma tumors in the peritoneal cavity without liver metastasis in the mouse." (PMID 16336680, 2005). "ICAM1 inhibition, but not VCAM1 inhibition reduced melanoma cell retention." (PMID 39875968, 2025). "Further, both melanoma cell lines do not express LFA-1 and do not bind to ICAM-1." (PMID 37894438, 2023). "Importantly, ICAM-1 is highly expressed in melanoma but not in most other tissues, accounting for CVA21-melanoma tropism." (PMID 34503272, 2021).